KIF2C (kinesin family member 2C)
Diseases named in the same sentence as KIF2C in open-access papers (continued):
Sharing a sentence is not in itself a finding about the gene and the disease.
prostate carcinoma (5 papers, 2012 to 2023). A carcinoma that arises from epithelial cells of the prostate gland. "Based on WGCNA module selecting and gene expression analysis, BUB1, KIF2C, CDC20, and PBK were eventually detected to be potentially associated with the clinical pathological features of prostate cancer." (PMID 35360870, 2022). "However, experimental validation of BUB1 and KIF2C in prostate cancer was unavailable in the HPA database, which were valuable to be verified based on more experiments." (PMID 35360870, 2022). "In our study, KIF2C performed as a risk prognostic factor, but no prognostic value of KIF2C in prostate cancer has been verified." (PMID 35360870, 2022).
COVID-19 (4 papers, 2022 to 2025). A disease caused by infection with severe acute respiratory syndrome coronavirus 2. "In KIRC, KIF2C is involved in immune-related processes such as “complement and coagulation cascade,” “cytokine-cytokine receptor interaction,” and also, KIF2C is associated with “Coronavirus disease-COVID-19”." (PMID 35685442, 2022). "The GSE167028 and GSE150392 datasets were subjected to a recent bioinformatic analysis, which unveiled six critical genes (CDK1, KIF20A, PBK, KIF2C, CDC20, and UBE2C) associated with COVID-19 myocarditis." (PMID 40230577, 2025). "As for the remaining genes, CDC20 and KIF2C were identified as target genes of COVID-19 by bioinformatics means and machine learning." (PMID 35749386, 2022). "Eventually, 6 genes (CDK1, KIF20A, PBK, KIF2C, CDC20, UBE2C) were identified by CytoHubba plug-in of Cytoscape as critical genes of COVID-19 Myocarditis for future study." (PMID 35749386, 2022). "Based on 5 algorithms of the CytoHubba plug-in, six genes (CDK1, KIF20A, PBK, KIF2C, CDC20, UBE2C) were confirmed as critical genes related to COVID-19 Myocarditis." (PMID 35749386, 2022). "KIF2C and PCLAF have been identified as critical genes in COVID-19 and may be potential biomarkers and treatment targets." (PMID 41000417, 2025). "It is worth highlighting that critical genes (CDK1, KIF20A, PBK, KIF2C, CDC20, UBE2C) may be potential biomarkers and treatment targets of COVID-19 Myocarditis for future study." (PMID 35749386, 2022). "Based on topological algorithms (i.e., degree), in this study, CDK1, KIF20A, PBK, KIF2C, CDC20, and UBE2C were identified as critical genes that may be potential biomarkers for COVID-19 Myocarditis." (PMID 35749386, 2022).
esophageal squamous cell carcinoma (4 papers, 2016 to 2022). Esophageal squamous cell carcinoma (ESCC) is a type of esophageal carcinoma (EC) that can affect any part of the esophagus, but is usually located in the upper or middle third. "For example, KIF-2C was considered to be associated with the poor prognosis of male patients with esophageal squamous cell carcinoma." (PMID 32549756, 2020).
thyroid cancer (4 papers, 2018 to 2023). "Expression levels of TRIP13, TPX2, DLGAP5, KIF2C and TTK were associated with shorter disease free survival (DFS) among differentiated thyroid cancer." (PMID 30386706, 2018).
triple-negative breast carcinoma (4 papers, 2023 to 2025). An invasive breast carcinoma which is negative for expression of estrogen receptor (ER), progesterone receptor (PR), and human epidermal growth factor receptor 2 (HER2). "Among different subtypes, triple-negative breast cancer showed highest KIF2C expression while luminal A subtype had lowest expression." (PMID 37016301, 2023).
pancreatic cancer (3 papers, 2023 to 2024). "In support of this, two recent studies with pancreatic cancer (PCa) and two with PAAD found that KIF2C was highly upregulated in pancreatic cancer tissues and correlated with poor patient prognosis and survival." (PMID 38344808, 2024). "Further analysis using the public database GEPIA revealed that the expression of six genes (PLK1, SPC24, KIF2C, TOP2A, MKI67, and KIF4A) was significantly associated with overall survival in pancreatic cancer patients." (PMID 38250721, 2024). "Among these, PLK1, SPC24, KIF2C, TOP2A, MKI67, and KIF4A, have been implicated in cancer development and serve as important biomarkers of proliferative activity in pancreatic cancer." (PMID 38250721, 2024). "At present, the therapeutic effect of pancreatic cancer is limited; we hope that the target of KIF2C can provide new ideas for its treatment, so that patients who cannot receive timely surgical treatment can obtain a better prognosis." (PMID 36900292, 2023). "After completing the experiments in vivo and in vitro, we have to think about how KIF2C has such an effect on pancreatic cancer cells." (PMID 36900292, 2023). "Patients with advanced TNM pancreatic cancer had higher KIF2C expression levels compared to patients with early TNM." (PMID 36900292, 2023). "Following this, via flow cytometry, we detected that KIF2C affects the cell cycle of pancreatic cancer and verified the expression of some genes related to the underlying mechanism in the sequenced transcriptome data." (PMID 36900292, 2023). "The difference in the expression of KIF2C in pancreatic cancer makes us think about the relationship between KIF2C and survival." (PMID 36900292, 2023). "In this study, we first identified the high expression of KIF2C in pancreatic cancer by TCGA and subsequently verified this finding at the DNA and protein levels." (PMID 36900292, 2023). "In this study, we report that the expression of KIF2C in pancreatic cancer is increased, and it is closely connected to the tumor stage and prognosis of patients." (PMID 36900292, 2023). "Both in vitro and in vivo experiments show that the expression level of KIF2C affects the invasion, metastasis, and proliferation of pancreatic cancer." (PMID 36900292, 2023). "After validating the cell lines, we extracted the cancer and paired adjacent cancer RNAs from pancreatic cancer patients and detected the relative expression of KIF2C by qPCR after reverse transcription." (PMID 36900292, 2023). "Through in vivo and in vitro experiments, we confirmed that KIF2C affects the proliferation, invasion, and metastasis of pancreatic cancer." (PMID 36900292, 2023). "Based on clinical specimens, we found that KIF2C is abnormally expressed in pancreatic cancer, related to the stage of the patient." (PMID 36900292, 2023). "The expression level of KIF2C in pancreatic cancer was also higher than that in normal tissues." (PMID 36900292, 2023). "Interference with KIF2C can effectively reduce the invasiveness of pancreatic cancer, which may become a promising target for the treatment of this cancer." (PMID 36900292, 2023). "The effect of KIF2C on pancreatic cancer may not only be limited to the development of PDAC but may also pull the “trigger” and cause tumorigenesis." (PMID 36900292, 2023). "This means that KIF2C may be an important protein in the occurrence and development of pancreatic cancer." (PMID 36900292, 2023). "Nevertheless, the role of KIF2C in pancreatic cancer is unknown." (PMID 36900292, 2023). "Therefore, we speculate that KIF2C may play a crucial role in the occurrence and development of pancreatic cancer." (PMID 36900292, 2023). "However, we did not conduct an in-depth exploration of the signal pathway of KIF2C’s function, revealing only the role of KIF2C in pancreatic cancer and the pathways and genes that may be related to it, which is also where this study needs to be improved." (PMID 36900292, 2023).
pancreatic cancer (continued). "CDC20 may also be involved in the role of KIF2C in pancreatic cancer." (PMID 36900292, 2023). "By analyzing the depth and range of staining, the expression level of KIF2C in pancreatic cancer was prominently higher than that in normal or highly differentiated tissues." (PMID 36900292, 2023). "Irrespective of the analysis of bioinformatics or the verification of clinical samples, KIF2C in pancreatic tumor cells is much higher than that in a normal pancreas." (PMID 36900292, 2023). "We noticed that there is no relevant literature to show whether the difference in KIF2C expression has an influence on pancreatic cancer." (PMID 36900292, 2023). "This means that the overexpression of KIF2C in pancreatic cancer is not meaningless." (PMID 36900292, 2023).
Azoospermia (2 papers, 2022 to 2025). Absence of any measurable level of sperm,whereby spermatozoa cannot be observed even after centrifugation of the semen pellet. "Additionally, transcriptomic and single‐cell RNA sequencing analyses have identified KIF2C as one of four novel hub genes linked to Klinefelter syndrome, a major cause of azoospermia and oligospermia due to impaired spermatogenesis." (PMID 40433108, 2025). "Therefore, the development of drugs related to the KIF2C gene and its encoded protein may provide a new direction and idea for the treatment of patients with KS azoospermia or oligospermia." (PMID 35622500, 2022). "Our results demonstrated that Kif2c KO male mice exhibit meiotic arrest and severe hypospermatogenesis, resulting in nonobstructive azoospermia (NOA)." (PMID 40433108, 2025). "Analyses of Gene Expression Omnibus (GEO) datasets from patients with nonobstructive azoospermia show that KIF2C is significantly downregulated in spermatogenesis." (PMID 40433108, 2025). "Kif2c KO mice exhibit nonobstructive azoospermia; however, the severity of hypospermatogenesis remains unclear." (PMID 40433108, 2025).
glioblastoma (2 papers, 2018 to 2024). The most malignant astrocytic tumor (WHO grade IV). "For example, the expression of KIF2C, which promotes mitotic chromosome segregation, is considerably upregulated in glioblastoma." (PMID 30038719, 2018).
Infertility (2 papers, 2021 to 2022). "The new findings of this study provide important insights into the infertility of KS, and KIF2C may be a biomarker leading to impaired sperm development in KS, providing a strong basis for accurate diagnosis and precise treatment of KS." (PMID 35622500, 2022). "Furthermore, we made the validation of hub-gene (A total of 12 genes were identified as hub genes in testicular carcinoma) in male infertility by GSE4797, 145467, 108886 and 6872 and found TEKT2 and KIF2C might work in infertility." (PMID 34591790, 2021). "Furthermore, we found KIF2C might act in infertility and testis cancer through DEG, functional annotation and pathway, protein interaction network and module analysis." (PMID 34591790, 2021). "We found KIF2C-miRNAs (has-miR-3154, 6075, 6760-5p, 1251-5p, 186-sp)-TFs (EP300, SP1) might work in spermatozoa of infertile men." (PMID 34591790, 2021).
male infertility (2 papers, 2021 to 2025). The inability of the male to effect fertilization of an ovum after a specified period of unprotected intercourse. "Several studies have suggested a potential association between KIF2C and male infertility." (PMID 40433108, 2025). "To understand the cause of male infertility, we analyzed the testes of Kif2c KO mice." (PMID 40433108, 2025). "Global Kif2c KO mice generated in this study may provide a model to study meiotic abnormalities and male infertility, which may lead to a better understanding of the etiology of NOA and the development of new therapeutic strategies." (PMID 40433108, 2025). "Recent transcriptomic analyses suggest a potential link between KIF2C and male infertility." (PMID 40433108, 2025). "Global Kif2c KO mice were obtained and showed male infertility." (PMID 40433108, 2025). "In conclusion, using global Kif2c KO mice, we reveal that Kif2c deletion results in NOA, which is one of the most severe causes of male infertility without curative treatment available." (PMID 40433108, 2025). "Through validation of hub-gene (A total of 12 genes were identified as hub genes in testicular carcinoma) in male infertility by GSE4797 set, we found expression of KIF2C between more than or equal to John score 5 and less than 5 existed significant difference." (PMID 34591790, 2021).
melanoma (2 papers, 2019 to 2022). A malignant, usually aggressive tumor composed of atypical, neoplastic melanocytes. "In our study, we found that the expression of KIF2C was significantly elevated in SKCM tissues compared to nevus tissues and associated with poor prognosis in melanoma patients by bioinformatic research." (PMID 35991567, 2022).
metastatic melanoma (2 papers, 2021 to 2022). A melanoma that has spread from its primary site to another anatomic site. "It has previously been reported that T cells from patients with metastatic melanoma could recognize mutated kinesin family member 2C (KIF2C) antigen." (PMID 33995482, 2021). "KIF2C is likely to be the essential gene for carcinogenesis and may be closely involved in tumor-infiltrating lymphocytes of cancer immunotherapy for patients with metastatic melanoma." (PMID 35991567, 2022).
acute lymphoblastic leukemia (1 paper, 2024). Leukemia with an acute onset, characterized by the presence of lymphoblasts in the bone marrow and the peripheral blood. "One study showed that KIF2C was overexpressed in patients with relapsed acute lymphoblastic leukemia (ALL)." (PMID 38344808, 2024).
Alzheimer disease (1 paper, 2022). A progressive, neurodegenerative disease characterized by loss of function and death of nerve cells in several areas of the brain leading to loss of cognitive function such as memory and language. "Particularly, KIF2C is associated with Alzheimer’s disease and suicidality psychiatric disorders." (PMID 35138249, 2022). "In vitro study showed that Oligomeric amyloid-β (Aβ) directly inhibits the MT-dependent ATPase activity of KIF2C and leads to abnormal mitotic spindles, which may cause chromosome mis-segregation and increased aneuploid neurons and thereby contributes to the development of Alzheimer’s disease." (PMID 35138249, 2022). "Interestingly, Oligomeric amyloid-β directly inhibits the MT-dependent ATPase activity of KIF2C in vitro, and thereby leads to the generation of defective mitotic structures which may contributes to the development of Alzheimer’s disease." (PMID 35138249, 2022). "Furthermore, KIF2C was recently discovered as a blood biomarker for suicidal ideation in psychiatric patients, such as patients with schizophrenia.Therefore, KIF2C could be a therapeutic target for Alzheimer’s disease or suicidality psychiatric disorders." (PMID 35138249, 2022).
Anxiety (1 paper, 2022). Intense feelings of nervousness, tension, or panic often arise in response to interpersonal stresses. "The KIF2C cKO mice showed normal motion and anxiety levels in the open field test and elevated zero maze compared to those of the WT mice, and had normal grooming frequencies in the commonly used repetitive behavioral test." (PMID 35138249, 2022).
breast invasive carcinoma (1 paper, 2024). "Furthermore, a strong linear correlation was observed for the KIF2C gene (Pearson correlation coefficient, r = 0.712; p < 1.16 × 10−17) in the breast invasive carcinoma (BRCA) cancer type, and a moderate linear correlation for RAD51AP1 (Pearson correlation coefficient, r = 0.308; p = 0.0076)." (PMID 38763334, 2024).
cervical adenocarcinoma (1 paper, 2021). An adenocarcinoma arising from the cervical epithelium. "Not only that, the expression of KIF2C was higher in squamous cervical carcinoma than cervical adenocarcinoma." (PMID 35153749, 2021).
Cirrhosis (1 paper, 2022). A chronic disorder of the liver in which liver tissue becomes scarred and is partially replaced by regenerative nodules and fibrotic tissue resulting in loss of liver function. "It is concluded that BUB1B, NUSAP1, TTK, HMMR, CCNA2, and KIF2C can be considered as potential novel molecular indicators for the onset and development of HCC, since they are linked to the transition from cirrhosis to HCC." (PMID 36199789, 2022).
Fanconi anemia (1 paper, 2020). Fanconi anemia (FA) is a hereditary DNA repair disorder characterized by progressive pancytopenia with bone marrow failure, variable congenital malformations and predisposition to develop hematological or solid tumors.
hepatitis B (1 paper, 2022). "Based on the HCC gene dataset, we used weighted gene coexpression network analysis for identifying MRGs linked to hepatitis B. An MRG prognostic index (MRGPI) with two genes, ATIC and KIF2C, was constructed using Cox regression analysis, an independent prognostic factor." (PMID 36072970, 2022).
lentivirus infection (1 paper, 2022). Virus diseases caused by the Lentivirus genus. "To validate, SKCM cell culture and lentivirus infection was performed to reveal the expression and behavior pattern of KIF2C." (PMID 35991567, 2022).
leukemia (1 paper, 2020). A malignant (clonal) hematologic disorder, involving hematopoietic stem cells and characterized by the presence of primitive or atypical myeloid or lymphoid cells in the bone marrow and the blood. "Although many studies show that KIF2C is an oncogenic factor in various solid tumors, we demonstrated for the first time that KIF2C plays an oncogenic role in leukemia." (PMID 32354205, 2020). "However, there has been limited research on the role of KIF2C and its relationship to KIF18B in leukemia." (PMID 32354205, 2020).
Lynch syndrome (1 paper, 2013). An autosomal dominant hereditary neoplastic syndrome characterized by the development of colorectal carcinoma and a high risk of developing endometrial carcinoma, gastric carcinoma, ovarian carcinoma, renal pelvis carcinoma, and small intestinal carcinoma. "Lynch syndrome tumors showed up-regulation of 1129 genes, e.g. genes involved in G1/S transition (CCNE, CCNH, E2F2 and CDK2), DNA replication (CDC45, RPA1, RFC5, MCM4 and POLD3) and chromosomal organization and mitosis (CCNB2, MLF1IP, CASC5, KIF2C and PLK4), which is in line with previous findings." (PMID 23951239, 2013).
metastatic tumor (1 paper, 2025). "Given the established role of KIF2C in enhancing the malignancy of various cancers, it is reasonable to hypothesize that KIF2C may also play a significant role in osteosarcoma (OS), a highly aggressive and metastatic tumor." (PMID 40292920, 2025).
osteosarcoma (1 paper, 2025). A usually aggressive malignant bone-forming mesenchymal neoplasm, predominantly affecting adolescents and young adults. "Although kinesin family member 2C (KIF2C) is implicated in various cancers, its role in osteosarcoma (OS) and the associated inflammatory microenvironment remains unclear." (PMID 40292920, 2025). "Osteosarcoma, characterized by its rapid progression and high metastatic potential, might share some of the carcinogenic properties associated with KIF2C expression in other cancers." (PMID 40292920, 2025). "Future studies should prioritize the experimental validation of butein's effects on osteosarcoma cells, including its ability to inhibit KIF2C activity and its impact on tumor growth and metastasis." (PMID 40292920, 2025). "Through wound‐healing, apoptosis, colony formation, and Transwell migration assays, we found that overexpression of KIF2C significantly enhanced the invasion ability of osteosarcoma cells." (PMID 40292920, 2025). "Future studies should investigate whether KIF2C directly modulates Tex cell differentiation or function, and whether targeting KIF2C could reverse T cell exhaustion and enhance the efficacy of immunotherapy in osteosarcoma." (PMID 40292920, 2025). "Finally, IHC results show that KIF2C expression is significantly increased in osteosarcoma tissue, particularly in the perinuclear regions of tumor cells, where staining intensity is notably higher." (PMID 40292920, 2025). "In conclusion, the abnormal expression of KIF2C can lead to chromosome structural instability and DNA damage, which may support the close relationship between KIF2C and the occurrence and development of osteosarcoma." (PMID 40292920, 2025).